RN7SKP272 (RN7SK pseudogene 272)
Gene: Miscellaneous RNA gene on chromosome 1 (89,987,713 to 89,987,944, reverse strand). Ensembl gene ENSG00000252797.
Homologues: Orthologues: chimpanzee 7SK (99% identical), mouse Gm55242 (38% identical). Paralogues in human: RN7SKP180 (59% identical), RN7SKP226 (59% identical), RN7SKP1 (59% identical), RN7SKP124 (59% identical), RN7SKP134 (59% identical), RN7SKP110 (58% identical), RN7SKP130 (58% identical), RN7SKP170 (58% identical), RN7SKP176 (58% identical), RN7SKP184 (58% identical), RN7SKP203 (58% identical), RN7SKP231 (58% identical), and 283 more.